MDK (midkine)
Diseases named in the same sentence as MDK in open-access papers (continued):
Sharing a sentence is not in itself a finding about the gene and the disease.
rheumatoid arthritis (5 papers, 2008 to 2025). A chronic, systemic autoimmune disorder characterized by inflammation in the synovial membranes and articular surfaces. "In both inflammatory and malignant conditions—particularly in inflammatory bowel diseases such as Crohn’s disease and ulcerative colitis, as well as in MS and rheumatoid arthritis (RA)—MDK has emerged as a cytokine of diagnostic significance." (PMID 40500394, 2025). "Recently, there is increasing evidence that midkine is implicated in autoimmune and inflammatory diseases, such as rheumatoid arthritis (RA), multiple sclerosis (MS) and inflammatory bowel disease (IBD)." (PMID 27903979, 2017). "Also, MDK expression is associated with various inflammatory diseases, including rheumatoid arthritis and atherosclerosis." (PMID 23976985, 2013). "In spite of its restricted expression in adult kidney, MDK expression is increased in disease conditions such as rheumatoid arthritis and cancer." (PMID 18275606, 2008). "MDK inhibitors have shown therapeutic efficacy in several diseases, including renal disorders, postoperative hypertension, rheumatoid arthritis (RA), multiple sclerosis (MS), and various cancers." (PMID 40500394, 2025).
atherosclerosis (4 papers, 2013 to 2022). A disease characterized by the build-up of fatty material and calcium deposition in the arterial wall resulting in partial or complete occlusion of the arterial lumen. "Among different cytokines, Midkine, a small growth factor protein 13 kDa in size, is an interesting target that was reported to be highly expressed in inflammatory kidney diseases and atherosclerosis." (PMID 36364277, 2022). "Midkine increased the proliferation of smooth muscle cells, inhibited apoptosis of macrophages, and promoted atherosclerosis plaque formation in mice models." (PMID 36364277, 2022). "Furthermore, midkine promotes lipid accumulation in macrophages and enhances vascular inflammation, which are key points during atherosclerosis." (PMID 36364277, 2022).
autoimmune disease (4 papers, 2017 to 2023). A disorder resulting from loss of function or tissue destruction of an organ or multiple organs, arising from humoral or cellular immune responses of the individual to their own tissue constituents. "Emerging evidence suggests that two heparin-binding growth factor, midkine and pleiotrophin are implicated in the pathogenesis of autoimmune diseases including SLE." (PMID 27903979, 2017). "MDK has been found to play an important role in nervous system development during embryonic development, as well as in the regulation of inflammatory reactions associated with autoimmune diseases and cancer." (PMID 37193028, 2023). "In recent years, there is growing evidence that midkine are implicated in autoimmune diseases." (PMID 27903979, 2017). "All these findings suggest that midkine may be implicated in the pathogenesis of autoimmune diseases." (PMID 27903979, 2017). "The clinical efficacy of anti-MDK aptamers has additionally been shown for autoimmune disorders of the CNS, such as MS." (PMID 38098484, 2023). "Increased levels of circulating MDK have not only been described in peripheral autoimmune diseases but also in other inflammatory conditions like ulcerative colitis (UC) and Crohn’s disease (CD), two main forms of inflammatory bowel diseases (IBDs)." (PMID 38098484, 2023). "Collectively, the blockade of MDK harbors great potential as therapeutic strategy in neoplastic and autoimmune diseases of both the periphery and the CNS." (PMID 38098484, 2023). "Despite increasing evidence of the involvement of midkine in the pathogenesis of autoimmune diseases, the data on pleiotrophin in these diseases are very limited." (PMID 27903979, 2017). "Our results are similar to the previous relevant studies in other autoimmune diseases, such as elevated plasma midkine level and its association with IL-17 in SLE patients, and elevated plasma midkine level in RA." (PMID 27903979, 2017). "Additionally, MDK contributes to the onset and progression of inflammatory and autoimmune diseases through its chemoattractant properties and the suppression of regulatory mechanisms." (PMID 38098484, 2023). "Collectively, these evidence suggest that midkine may play a key role in the pathogenesis of autoimmune diseases including SLE, inhibiting midkine therefore might be useful for attenuating inflammation-related symptoms in these diseases." (PMID 27903979, 2017). "While inhibition or blockade of MDK signaling may be a promising option for neoplastic, inflammatory, or autoimmune diseases affecting the CNS, endogenous or exogenous increase of MDK levels could improve the outcome in the context of acute CNS injuries and ischemia." (PMID 38098484, 2023).
chronic kidney disease (4 papers, 2020 to 2025). Impairment of the renal function secondary to chronic kidney damage persisting for three or more months. "Animal models and small case control studies have implicated MDK as a pathological biomarker in chronic kidney diseases (CKD), however this is yet to be confirmed in prospective human studies." (PMID 32879333, 2020). "Some studies reported that MK prevented cardiac remodelling after MI or congestive heart failure, while some studies found that MK deteriorated cardiac remodelling induced by pressure overload or chronic kidney disease using Midkine‐transgenic or knockout mice." (PMID 32701210, 2020).
colon cancer (4 papers, 2010 to 2022). "Midkine was upregulated in advanced cancers in rectum, being significantly associated with overall disease stage and lymph node involvement, but downregulated in advanced colonic cancers." (PMID 22562257, 2012). "We found midkine and VEGF to be independent predictors of weight loss in patients with colon cancer." (PMID 20920199, 2010). "Recently, we identified, for the first time, that MDK is a critical downstream target of IFN-γ in cancers of various origins, including kidney, lung, cervical, breast, and colon cancers." (PMID 36672515, 2022). "C-reactive protein (CRP), albumin, IL-1α, IL-1β, IL-6, IL-8, IL-10, TNF-α, midkine, VEGF-A, VEGF-C, leptin, adiponectin, and ghrelin serum levels are studied in 126 colon cancer patients and 36 healthy subjects." (PMID 20920199, 2010).
Crohn disease (4 papers, 2017 to 2025). A gastrointestinal disorder characterized by chronic inflammation involving all layers of the intestinal wall, noncaseating granulomas affecting the intestinal wall and regional lymph nodes, and transmural fibrosis. "Due to its close association with disease activity, MDK is considered an important biomarker in both Crohn’s disease and celiac disease (CeD)." (PMID 40500394, 2025). "In CD, serum midkine levels was positively associated with Crohn's Disease Activity Index, and midkine was found to be a sensitive biomarker of diagnostic value comparable with the gold standard CRP in this disease." (PMID 27903979, 2017). "In line with our findings, we suggest the theory that MDK inhibitors may be useful in treating Crohn’s disease." (PMID 31905498, 2020).
embryonal carcinoma (4 papers, 2013 to 2023). A non-seminomatous malignant germ cell tumor characterized by the presence of large germ cells with abundant cytoplasm resembling epithelial cells, geographic necrosis, high mitotic activity, and pseudoglandular and pseudopapillary structures formation. "Midkine (MDK), encoded by the MDK gene, was first discovered through differential hybridization by examining the increased RNA levels of its cDNA in retinoic acid-induced differentiation in embryonal carcinoma cells." (PMID 37240085, 2023). "Midkine (MK) was discovered in the course of retinoic-acid-mediated differentiation of murine embryonic carcinoma cells during early stages of embryogenesis." (PMID 36204583, 2022). "Midkine (MK) is a heparin-binding growth factor with a molecular weight of 13 kDa, first isolated as a product of the retinoic acid-responsive gene in the embryonal carcinoma cell differentiation system." (PMID 24635859, 2014). "In 1988, the Muramatsu group first described midkine as a 13–15 KD heparin binding polypeptide present in embryonal carcinoma cells which acts to enhance neuronal cell survival and stimulate neurite extrusion." (PMID 24083030, 2013).
esophageal cancer (4 papers, 2016 to 2025). A primary or metastatic malignant neoplasm involving the esophagus. "In the study of esophageal cancer, the researchers identified midkine (MDK) as a novel partner of SRGN’s function." (PMID 38287411, 2024). "Correlations between the expression of midkine protein and the serum midkine concentrations have been established in esophageal cancer and head and neck squamous cancer." (PMID 27974680, 2016).
esophageal squamous cell carcinoma (4 papers, 2010 to 2025). Esophageal squamous cell carcinoma (ESCC) is a type of esophageal carcinoma (EC) that can affect any part of the esophagus, but is usually located in the upper or middle third. "Ligand - receptor pairs midkine - syndecan 4 (MDK - SDC4) and MDK - nucleolin (NCL), which is associated with tumor growth and communication between tumor cells and cancer-associated fibroblasts (CAFs) in esophageal squamous cell carcinoma, were also observed." (PMID 40036264, 2025). "It is also of interest that similar to CRP, circulating midkine and IL-8 have been found to reflect lymph node involvement in esophageal squamous cell carcinoma." (PMID 20920199, 2010). "One study completed in ESCC (esophageal squamous cell carcinoma) found that out of 66 ESCC samples studied using immunohistochemistry, MDK was over-expressed with a positive rate of 56.1% (37/66)." (PMID 37240085, 2023).
ischemia (4 papers, 2020 to 2023). A hypoperfusion of the BLOOD through an organ or tissue caused by a PATHOLOGIC CONSTRICTION or obstruction of its BLOOD VESSELS, or an absence of BLOOD CIRCULATION. "Aside from TBI, MDK is expressed in early stages of cerebral infarct, a condition where the blood supply to the brain is disrupted, leading to ischemia and hypoxia, and finally to necrotic tissue in the brain." (PMID 38098484, 2023). "MDK is primarily studied in conditions with malignancy, inflammation, and preexisting peripheral vascular disease or ischemia." (PMID 31905498, 2020). "Midkine (MK) is a multifunctional cytokine found upregulated in the brain in the presence of different disorders characterized by neuroinflammation, including neurodegenerative disorders and ischemia." (PMID 31996236, 2020). "Midkine role during IR injury seems to depend on the affected organ as the cytokine exerted antiapoptotic, thus protective activity in the heart but contributed to organ damage in the renal and hindlimb models of ischemia by promoting macrophage and neutrophil infiltration." (PMID 34884960, 2021).
liver cirrhosis (4 papers, 2015 to 2024). "As a result, serum MDK and OPN levels were comparable to α-FP levels as potential HCC diagnostic biomarkers in HCV patients with liver cirrhosis." (PMID 36901717, 2023). "According to a 2021 Egyptian study, patients with HCC (86 HCV induced) had significantly higher MDK levels than patients with liver cirrhosis and healthy controls (p < 0.001)." (PMID 36901717, 2023). "Serum MDK levels were higher in HCC patients compared with the liver cirrhosis and control groups." (PMID 38247828, 2024). "MDK levels were upregulated in HCC patients compared with liver cirrhosis patients." (PMID 38247828, 2024). "MDK was better than AFP in differentiating HCC patients from individuals with liver cirrhosis." (PMID 38247828, 2024). "This means that the well-known nonspecific elevations of AFP in patients with liver cirrhosis were not significantly elicited with serum MDK increasing its specificity as a novel diagnostic marker for HCC." (PMID 25737783, 2015). "The best cutoff values for MDK and AFP to discriminate HCC cases from those with liver cirrhosis were 0.387 and 88.5 ng/mL, respectively, with sensitivities (92.5 versus 40%), specificities (83.3 versus 96.7%), and accuracies (88.5 versus 68.2%), respectively." (PMID 25737783, 2015). "It was established that MDK levels in HCC patients were on average 5 times higher than in those with liver cirrhosis without HCC." (PMID 34513063, 2021). "No one in the healthy control group exceeded MDK cutoff level 0.38 ng/mL and only 5 patients (16.7%) from liver cirrhosis group exceeded this threshold." (PMID 25737783, 2015). "However, it is worth noting that MDK showed greater sensitivity compared with AFP in HCC diagnosis, especially in the early stages, highlighting its potential as a novel marker, especially in differentiating HCC from liver cirrhosis." (PMID 38247828, 2024). "-AFP was better than MDK in distinguishing HCC from non-HCC cases and HCV or HBV-associated HCC from liver cirrhosis.-MDK could distinguish NASH-related HCC from cirrhosis. -MDK was elevated 6 months prior to diagnosis in 67% of patients." (PMID 38247828, 2024). "In addition, serum MDK was not significantly higher in the liver cirrhosis group than that in healthy group (0.15 versus 0.125 ng/mL; P = 1.559), in contrast to serum AFP which was significantly elevated in the liver cirrhosis group when compared to healthy group (17.5 versus 1 ng/mL; P = 0.0001)." (PMID 25737783, 2015). "The study involved a total of 140 participants, encompassing 35 HCV patients without cirrhosis, 35 with HCV and liver cirrhosis, 35 with HCC on top of liver cirrhosis, and 35 healthy controls, and serum MDK levels were evaluated by ELISA." (PMID 38247828, 2024). "Specifically, in a recent study, serum MDK levels were assessed in 238 individuals, including 78 HCC patients with HCV-related HCC, 40 with HCV-related liver cirrhosis, 40 with chronic HCV without liver cirrhosis, and 80 healthy controls." (PMID 38247828, 2024).
myocardial infarction (4 papers, 2014 to 2018). Gross necrosis of the myocardium, as a result of interruption of the blood supply to the area, as in coronary thrombosis. "The pro-angiogenic effects of midkine have been implicated to be the major reason why midkine protects against cardiac remodeling after myocardial infarction." (PMID 29695980, 2018). "Although midkine has protective effects after myocardial infarction, it has also been shown to increase cardiac hypertrophy during pressure overload." (PMID 29695980, 2018). "Increased expression of MDK is pathologic in various cancers due to increased cell migration and survival, but can be beneficial in cardiovascular diseases by improving cardiomyocyte survival after myocardial infarction." (PMID 28920060, 2017). "In addition to gene expression, MDK protein was upregulated in the border zone of the myocardial infarction." (PMID 28920060, 2017). "Elevated midkine (MK) expression may contribute to ventricular remodeling and ameliorate cardiac dysfunction after myocardial infarction (MI)." (PMID 24635859, 2014).
myocarditis (4 papers, 2020 to 2025). Myocarditis is a condition that is characterized by inflammation of the heart muscle (myocardium). "In inflammatory diseases such as myocarditis, the interaction of MDK with the receptor LRP1 and members of the β2 integrin family is critical for MDK-induced PMN recruitment and neutrophil extracellular trap (NET) formation." (PMID 38098484, 2023). "For this reason, it is of particular interest that midkine has been found to be involved in promoting NETosis in myocarditis." (PMID 34439416, 2021).
Senile plaques (4 papers, 2011 to 2024). Senile plaques are extracellular deposits of amyloid in the gray matter of the brain. "Midkine is a heparine-binding cytokine, which regulates processes like tissue protection and inflammation, additionally, it is present in senile plaques of AD and therefore is suggested as a potential clinical target." (PMID 35944844, 2022). "Since staining intensity of midkine in senile plaques was similar to that in the embryonic brain, we infer that a similar level of midkine is locally present in the plaques." (PMID 21223602, 2011). "Midkine, Aβ, heparan sulfate proteoglycans with heparin-like domains and other molecules coexist in the brain tissue and senile plaques." (PMID 21223602, 2011).
Wilms tumor (4 papers, 2008 to 2023). An embryonal neoplasm characterized by the presence of epithelial, mesenchymal, and blastema components. "Wilms’ tumor is an embryonal malignancy of the kidney, and MDK is expressed in high levels during mid-gestation for developmental regulation of the embryo." (PMID 37240085, 2023). "MDK is also shown to impart cytoprotection to the Wilms’ tumor cells against cisplatin via the up-regulation of Bcl-2 proteins." (PMID 37240085, 2023). "Midkine was found to protect Wilms' tumor cells from cisplatin-induced apoptosis through Bcl-2 enhanced expression." (PMID 24083030, 2013). "A study has shown that all Wilms’ tumor samples studied have a high level of MDK, and there are two WT1 elements in the human MDK promoter region." (PMID 37240085, 2023).
asthma (3 papers, 2024 to 2025). "Collectively, these findings indicate that midkine is upregulated in asthma and promotes ASMC proliferation, an effect that can be suppressed by midkine knockdown." (PMID 40969143, 2025). "Midkine has also been implicated in another airway disease, COPD, in which the midkine‐Notch2 axis drives ASMC proliferation and remodeling, suggesting shared pathogenic mechanisms between COPD and asthma." (PMID 40969143, 2025). "Midkine levels are significantly elevated in asthma and promote PDGF‐BB‐induced ASMC proliferation, migration, ECM production, inflammatory cytokine release, and glycolysis via the PI3K/Akt signaling pathway." (PMID 40969143, 2025). "Serum midkine levels were significantly elevated in patients with asthma." (PMID 40969143, 2025). "Of note, MDK was known to play an important role in cell growth, proliferation, migration as well as angiogenesis, which was observed as an important signaling pathway for interaction between macrophages and endothelium in a monkey model of asthma." (PMID 38317239, 2024). "Our findings demonstrate that midkine levels are significantly elevated in the serum of children with asthma and that PDGF‐BB stimulation increases midkine expression in human ASMCs, promoting proliferation." (PMID 40969143, 2025). "Small‐molecule or biologic midkine antagonists have been explored in other diseases, and the present data justify evaluating midkine inhibition or interrupting its downstream PI3K/Akt coupling as a strategy to blunt ASM‐centric remodeling and inflammation in asthma." (PMID 40969143, 2025). "It was noticed that the MDK–NCL ligand-receptor pair showed higher activity and possibility between epithelial cells in A group, indicating that NCL might be a significant receptor during cellular cross-talk in asthma exacerbation." (PMID 39917297, 2025).
brain tumors (3 papers, 2020 to 2025). "Aside from its numerous roles in tumor-formation and -resistance in peripheral tissues, MDK has also been implicated to play a role in the development and tumorigenicity of brain tumors." (PMID 38098484, 2023). "This review summarizes the modes of action and immunological functions of MDK both in the peripheral immune compartment and in the CNS, particularly in the context of traumatic brain injury, brain tumors, neuroinflammation, and neurodegeneration." (PMID 38098484, 2023). "In this review, we will summarize the involvement and function of MDK in the context of peripheral disorders and CNS pathologies, including brain injuries, brain tumors, as well as neuroinflammatory and neurodegenerative diseases." (PMID 38098484, 2023). "The abnormal regulation of MDK expression has been observed in brain tumours." (PMID 40468625, 2025). "Recent research has indicated that MDK functions as a key player in autoimmune disorders of the central nervous system (CNS), such as Multiple Sclerosis (MS) and is a promising therapeutic target for the treatment of brain tumors, acute injuries, and other CNS disorders." (PMID 38098484, 2023).